PGR (progesterone receptor)
Diseases named in the same sentence as PGR in open-access papers (continued):
Sharing a sentence is not in itself a finding about the gene and the disease.
tumor (continued). "All patients with an ER/PgR positive tumor received adjuvant hormone therapy: 26 (55.3%)." (PMID 35740668, 2022). "Age, race, TNM stages, tumor grades, estrogen receptor (ER)/progesterone receptor (PR), and human epidermal growth factor receptor-2 (HER-2) overexpression were found to be independent prognostic factors in female breast cancer, according to multivariate Cox regression and competing risks analyses." (PMID 35885460, 2022). "Clinical variables such as tumor size, estrogen, progesterone receptor positivity, HER2, and tumor grade, as well as some metabolic variables such as SUVpeak, SUVmean, and SUVmax, had a statistically significant association with the target variable (metabolic response)." (PMID 35740588, 2022). "For PgR − tumours with < 40% ER, 92% (81/88.3) of cases were PRs." (PMID 36096872, 2022). "Only one patient with ER+ and PgR+ tumor reached partial remission." (PMID 37435469, 2022). "Interestingly, no fibrinolytic markers other than PAI-1 activity and antigen showed potential association with tumour diameter, TNM classification, histological grade, oestrogen receptor expression, progesterone receptor expression and Ki67 activity." (PMID 35566525, 2022). "Nevertheless, it has been suggested that progesterone receptor (PR) expression in the tumor could be a predictive factor of the response to HT and should be tested before treatment initiation." (PMID 35629078, 2022). "However, a significant correlation between high levels of CD8+ cytotoxic T lymphocytes (CTLs) and ER- and progesterone-receptor (PR) status in the primary tumor was observed (p = 0.033 and p = 0.001, respectively)." (PMID 35626676, 2022). "As LGSOC is known to have a more indolent course and a poorer response to standard chemotherapy, there has been much interest in exploring the possible clinical significance of the high percentage of ER and progesterone receptor (PR) positivity in these tumours." (PMID 34125335, 2021). "The combination of the ER/PgR expression level of the tumor and a multigene assay might provide an improved prediction of the survival outcome of the patient." (PMID 34638491, 2021). "The direction of therapy is chosen based on tumor morphology, its grade and size, the presence of metastases to the lymph nodes, as well as gene expression of BC critical markers: ER, progesterone receptor (PR), and human epidermal growth factor receptor 2 (HER2)." (PMID 34572928, 2021). "This tumor has a higher expression of PgR along with moderate expression of ER." (PMID 33981288, 2021). "In consequence, when PgR expression is lost, ERα gains access to a broader range of translational machinery, which may promote tumor aggressiveness and growth." (PMID 34638241, 2021). "In fact, BC may either show primary PgR(−) status (in chemonaïve tumor sample), lose PgR expression during neoadjuvant treatment, or acquire PgR(−) phenotype in local relapse or metastasis." (PMID 34638241, 2021). "We hypothesize that a brief estradiol challenge will increase tumor progesterone receptor (PgR) levels only in tumors with functional ER." (PMID 33531464, 2021). "We report data for clinically prognostic subgroups: liver metastases, progesterone receptor status, tumor grade, bone-only disease, ECOG performance status, and treatment-free interval (TFI) from an additional 12-month follow-up (after final progression-free survival [PFS] readout)." (PMID 34158513, 2021). "In this work, we show that this PgR-based estradiol-challenge test, as an in vivo assessment of tumor ER functional status, would be a much stronger predictor of benefit from ET than the mere presence of ER and/or PgR by IHC in a biopsy sample of a single lesion." (PMID 33531464, 2021). "In this phase 2 clinical trial, authors demonstrate that the responsiveness to ET can be predicted by use of PET/CT with 21-[18F]fluorofuranylnorprogesterone (FFNP) to detect the change in tumor progesterone receptor (PgR) levels after a one-day estradiol challenge." (PMID 33531464, 2021).
tumor (continued). "Among the 105 patients, the study demonstrated that larger tumor size and lower progesterone receptor level at baseline and larger tumor size postoperative were statistically significantly associated with worse disease-free survival (DFS) (p = 0.004, p = 0.021, and p = 0.001, respectively)." (PMID 34631568, 2021). "Retrospective risk stratification according to tumor size, nodal status, disease stage, tumor grade, Ki67 level, and progesterone receptor status did not appear to be able to predict the response to extended ET." (PMID 33939116, 2021). "Moreover, TFF1 and PgR have both been identified as biomarkers of a better prognosis in ER + tumours." (PMID 34453638, 2021). "Interestingly, the expression level of ERa protein was positively correlated to a high tumor stage, whereas the expression level of PGR protein was inversely correlated to a high tumor stage in patients with OV (Both p < 0.05)." (PMID 34322374, 2021). "PgR expression at the molecular level could suggest the presence of a functional pathway between ER and PgR in the tumor cell after estrogen binding." (PMID 33670083, 2021). "In the integrated random forest model, the AUCs for predicting human epidermal growth factor receptor 2 positivity, estrogen receptor positivity, progesterone receptor positivity, ki67 positivity, high tumor grade, and molecular subtype were 0.86, 0.76, 0.69, 0.65, 0.75, and 0.79, respectively." (PMID 34885124, 2021). "Multivariable analysis using Cox proportional hazard models indicated that the associations of CD68 + CLS-B with DFS and OS were not altered after adjustment for clinicopathologic factors, including tumour and nodal stage, grade, ER/PgR status and treatment (surgery, chemotherapy, hormone therapy)." (PMID 34294716, 2021). "In the tumor dataset (case, n = 90), there were 81.11% estrogen receptor-positive (ER+ve), 75.56% progesterone receptor-positive (PR+ve), 78.89% human epidermal growth factor receptor 2 (HER2)-negative (HER2−ve), and only 8.89% triple-negative (ER−ve, PR−ve, and HER2−ve) receptor subtypes." (PMID 34359739, 2021). "Additionally, PgR mediates ERα chromatin binding to genes involved in cell death, apoptosis, and differentiation pathways and blocks ERα-dependent tumor growth." (PMID 34638241, 2021). "Moreover, the phase of the menstrual cycle at which the tumor is excised can influence the PgR status: carcinomas removed in the luteal phase more often display PgR(−) phenotype, compared to the follicular phase." (PMID 34638241, 2021). "In previous studies, the methylation of EphA5 was associated with later tumor stages and progesterone receptor-negative status in BC." (PMID 34221956, 2021). "Finally, the expression of ER and PgR was studied by immunohistochemistry in 36 paraffin embedded tumor samples belonging to ACC diagnosed patients." (PMID 33981288, 2021). "In METABRIC cohort, patients in hot T-cell infiltrated were significantly associated with higher tumor grade (p < 0.0001), ER negative (p < 0.0001), PgR negative (p < 0.0001), TN (p < 0.0001), and claudin-low (p < 0.0001), compared with other groups." (PMID 33396390, 2020). "Interestingly, they reached significant results for correlations of MGMT promoter methylation with clinicopathological markers such as tumor staging and grading and estrogen and progesterone receptor expression." (PMID 32841306, 2020). "However, there was a tendency for up-regulation of TG in the PgR-negative compared with PgR-positive tumor tissues." (PMID 32287294, 2020). "MiR-155 expression was associated with unfavorable prognostic indicators including high tumor grade (overall P = 0.0007; G2 vs. G3 P = 0.0053), reduced expression of ER (r = −0.243; P = 0.0002) and PgR (r = −0.240; P < 0.0001), and high Ki-67 expression (r = 0.215; P = 0.0005)." (PMID 32903519, 2020).
tumor (continued). "This panel included the vascular marker CD31, CAF markers (CD34, caveolin-1 (CAV-1) and alpha smooth muscle actin (αSMA)) and steroid hormone receptors (SHR: androgen receptor (AR), progesterone receptor (PR) and estrogen receptor alpha (ERα)) in paired prostate non-tumour (PNT) and PCa tissue." (PMID 33370412, 2020). "Whether these changes are the result of the chemotherapy-induced selection of pre-existing tumor cell clones, or of chemotherapy-induced epigenetic modifications leading to changes in the ERα/PgR expression, remains unclear." (PMID 33316954, 2020). "There were significant differences between the groups in cT (cT1, cT2 versus cT3) (P = 0.0103), the mean pathological tumor size (P = 0.0017), the mean pathological invasive tumor size (P < 0.0001), pT (P < 0.0001), ER (P = 0.0070), PgR (P = 0.0031), and Ly (P < 0.0001)." (PMID 32124121, 2020). "Furthermore, a multivariable analysis adjusted for tumor grade, size, PgR expression status, and lymph node involvement, suggested that the association is independent of these tumor characteristics, with rs57025206-associated HR: 6.19, 95% CI: 3.73–10.3." (PMID 32964118, 2020). "In case of MBC, ECOG status, age, oestrogen receptor, HER2 and progesterone receptor (PR) status of the tumour, time to metastasis, number of metastatic sites, line of therapy, type of therapy and log-transformed CTCs and tdEVs were evaluated as potential risk factors." (PMID 31937922, 2020). "No other associations were observed between the relative expression of CYP19A1 mRNA and the other variables studied, such as age, use of tobacco, menopausal status, grade, nodal status (N), tumor stage, estrogen and progesterone receptor, HER2 and histological type." (PMID 32460723, 2020). "Progesterone (PG), a female hormone, alters ERα chromatin binding events in malignant breast cancer through progesterone receptor (PGR), which changes gene expression patterns, and the administration of PG reduced E2-dependent tumor growth in mouse xenograft experiments with MCF-7 cells." (PMID 31978754, 2020). "After adjusted for tumor grade and progesterone receptor status, patients harboring GSTT1 null genotype had a lower risk of death compared with patients with GSTT1 present genotype (HR = 0.630 and 0.612) nevertheless, there was not statistically significant difference (P = 0.152 and 0.143)." (PMID 32856852, 2020). "Typical treatments for BC besides surgery include endocrine therapy, chemical therapy, and radiotherapy; these have led to increased survival rates in majority of patients since most of the tumor cell express and respond to receptors for estrogen and progesterone receptor." (PMID 33718103, 2020). "We identified an increased abundance of triacylglycerols (TG) ≥ C-48 with moderate or multiple unsaturation in fatty acyl chains and down-regulated ether-phosphatidylethanolamines (PE) (C-34 to C-38) in cell lines representing estrogen receptor and progesterone receptor positive tumor subtypes." (PMID 32287294, 2020). "Indeed, ERα and PgR status is assessed by means of IHC, which evaluates the proportion of tumor cells expressing ERα or PgR, and which dichotomizes BC cells as HR+ or HR− based on a cut-off point of 1% for both proteins." (PMID 33316954, 2020). "However, the ER and PgR expressions of sirolimus-treated and sirolimus + sunitinib treated tumor are significantly lower compared to control group." (PMID 33112549, 2020). "About 30% of both ER + and progesterone-receptor-positive (PR+) tumours are not susceptible to endocrine treatment." (PMID 31752564, 2020).
tumor (continued). "Luminal B-like tumours have lower expression of ER and PgR compared to luminal A-like and higher histological grade tumours, which may explain this finding." (PMID 32726924, 2020). "Indeed, a subset of DFSP tumours have shown progesterone receptor positivity, suggesting a role of gender in its tumourigenesis." (PMID 33014128, 2020). "Ki-67 and PgR were assessed with immunohistochemistry for the tumor after surgery." (PMID 31975992, 2019). "As expected, expression of the oestrogen (ESR1)/progesterone (PGR) and HER2 (ERBB2) genes were highest in the luminal and HER2-enriched subtypes respectively, and as shown by others, expression of PGR was lower in luminal B tumours relative to luminal A (“PGR”, P < 0.001)." (PMID 30819233, 2019). "Tumor cells were positive for vimentin, ER, PgR, and desmin." (PMID 31240143, 2019). "The associations between mammographic casting-type calcification and other clinicopathological factors, including tumor size, node status, grade, progesterone receptor (PR) status, estrogen receptor (ER) status, and human epidermal growth factor receptor 2 (HER2) status, were analyzed." (PMID 31332233, 2019). "Additionally, surgical resection of the tumor and nodule was performed for histological analysis and immunohistochemical assays for estrogen receptor (ER) and progesterone receptor (PR)." (PMID 31804368, 2019). "Hormone-dependent breast cancer refers to that when tumor cells show positive expression of estrogen receptor (ER)/progesterone receptor (PR) and the growth and proliferation of tumor cells are regulated by estrogen and progesterone, antiestrogenic drugs must be used for treatment." (PMID 30911319, 2019). "The morphology of daughter cells was similar to parental tumor, indeed they expressed cytokeratin, vimentin, estrogen receptor-α (ERα), and PgR suggesting that a small population of cells is able to maintain features of parental tumor and to differentiate in vivo." (PMID 31752447, 2019). "Clinical parameters such as tumor size, lymph node involvement, histological grade, age and the expression of estrogen receptor (ER), progesterone receptor (PGR), and epidermal growth factor receptor 2 (HER2) biomarkers are responsible of its high clinical heterogeneity." (PMID 31057614, 2019). "Tumor size was statistically significant with RFS in both PgR status." (PMID 31975992, 2019). "Clinicians rely on traditional clinico-pathological, and readily available, tumor markers such as estrogen receptor (ER), progesterone receptor (PR), and human epithelial receptor-2 (HER-2) because they are reliable, inexpensive, and useful for therapeutic decision making." (PMID 29783652, 2018). "Analysis of clinical factors confirmed the following to have prognostic value: bone-only disease, liver metastases, tumor grade, progesterone receptor status, performance status, treatment-free interval (TFI) from the end of adjuvant ET, and time from diagnosis to recurrence." (PMID 30588487, 2018). "The collection of the human breast carcinomas used for the evaluation of p110δ levels was consisting of estrogen receptor (ER)- and/or progesterone receptor (PR)- positive, as well as ER-and/or PR-negative tumours whereas all tumours were human epidermal growth factor receptor 2 (HER2) negative." (PMID 29880805, 2018). "In the CEA-high subset, significantly higher frequencies were observed for postmenopausal status (p < 0.0001), larger tumor size (p < 0.0001), lymph node metastasis (p = 0.036), progesterone receptor (PgR) negativity (p = 0.005), and HER2 positivity (p = 0.044)." (PMID 29433529, 2018).
tumor (continued). "Age, breast surgery, menopausal status, tumor size, positive lymph nodes, ER/PgR status, Ki67, TILs, subtypes, adjuvant hormonal therapy, and adjuvant radiotherapy were statistically significant or marginally significant in the univariate analysis for DFS and OS." (PMID 30240146, 2018). "All patients had HR+ tumours (ER+ = 145, 94.2%; PgR+ve = 132, 85.7%)." (PMID 30159129, 2018). "In addition, GJA1 does not vary directly with ESR1 and HER2 mRNA and protein levels but shows a stronger correlation with PGR mRNA and PR protein in tumor samples." (PMID 29495625, 2018). "Briefly, ER and PgR were considered positive if staining was present in ≥1% of tumor cell nuclei." (PMID 30521571, 2018). "Compared to the other subgroups, FOXA1-/AR- BC phenotype was more frequently associated with high histological grade, large tumor size, no expression of ER and PgR and high proliferation index (P < 0.001)." (PMID 29970021, 2018). "In multivariate analysis, PITX2 hypermethylation evolved as a significant marker to predict outcome, when assessed together with the parameters age at the time of surgery, tumor stage, nuclear grade, progesterone receptor status, and adjuvant endocrine therapy." (PMID 29138528, 2017). "The PDW correlated with tumor size, estrogen receptor status, and progesterone receptor status." (PMID 29216259, 2017). "Initial investigation demonstrates that the existence of progesterone receptor might be a improved indicator of tumor hormone dependence than quantitative estrogen receptor." (PMID 28969709, 2017). "Traditional prognostic factors currently used to guide the use of systemic therapy and predict outcome include tumor size, lymph node involvement, histological grade, age, race, estrogen receptor (ER), progesterone receptor (PR) and epidermal growth factor receptor (HER2) status." (PMID 28122328, 2017). "An immunohistochemical (IHC) analysis demonstrated that the tumor was moderately positive for estrogen receptor (ER) at 15%, strongly positive for progesterone receptor (PR) at 50%, Ki-67 unfavorable at 30%, and HER2/NEU-positive by fluorescence in situ hybridization (FISH)." (PMID 29344435, 2017). "However, most of these prognosis factors rely on changes in the status of the patient′s tumor, such as changes in the tumor diameter, axillary lymph node status, histologic grade, estrogen receptor (ER) status and progesterone receptor (PR) status." (PMID 27564264, 2017). "The miR17/miR27b pair best discriminated samples with different tumour grades, but others correlated better with lymph node status, tumor size and oestrogen/progesterone receptor status, so that multiple marker pairs are required to characterize a tumor sample." (PMID 29050357, 2017). "Grade and progesterone receptor status were the highest predictors of both low-risk and high-risk ODXRS, followed by age, tumor size, histologic tumor type and lymph-vascular invasion (C-indexes-.0.85 vs. 0.88 for TAILORx-trial vs. commercial cut-off values, respectively)." (PMID 28243897, 2017). "Patients (pts) were stratified by progesterone receptor status and tumor size and randomized 1:1:1." (PMID 28454587, 2017). "Reduced BRCA1 expression was associated with high tumor grade and negative hormone receptors (estrogen receptor, progesterone receptor and Her2)." (PMID 28863181, 2017). "Lactation proteins as tumor targets are especially amenable to our proposed strategy of antigen amplification via ER antagonism since their production is known to be highly regulated by the estrogen and progesterone receptor signaling." (PMID 28430646, 2017). "Moreover, although both BC subtypes are classified as HER2-, they differ in estrogen/progesterone receptor status, tumor biology and clinical course of disease." (PMID 27888801, 2017).